ATM (ATM serine/threonine kinase)
Diseases named in the same sentence as ATM in open-access papers (continued):
Sharing a sentence is not in itself a finding about the gene and the disease.
breast cancer (continued). "Based on the similar roles played by ATM and ATR as sensors of DNA damages, ATR may be considered a putative candidate gene that could possibly explain a fraction of the remaining familial breast cancer risk." (PMID 17010193, 2006). "All of the tagSNPs in the CHEK2 and ERBB2 genes and two of the tagSNPs in the ATM gene were not only genotyped in breast cancer cases and controls who participated through blood sample donation, but were also genotyped in breast cancer cases who participated through tissue sample donation." (PMID 17132159, 2006). "In this study, several ATM SNPs were seemingly associated with breast cancer risk in Jewish non-Ashkenazi women at high-risk for breast cancer." (PMID 16622469, 2006). "Subsequently, ATM haplotyping of high-risk, non-Ashkenazi Jews was performed on 66 women with breast cancer and 76 asymptomatic." (PMID 16622469, 2006). "We conclude that a specific ATM SNP and a specific haplotype are associated with increased breast cancer risk in high-risk non-Ashkenazi Jews." (PMID 16622469, 2006). "In conclusion, the present study suggests that a specific ATM SNP seemingly contributes to breast cancer predisposition in Jewish non-Ashkenazi high-risk women in Israel." (PMID 16622469, 2006). "Although ataxia-telangiectasia mutated (ATM) heterozygous deficiency has been proposed to increase susceptibility to breast cancer, some studies have not found excess risk." (PMID 15642165, 2005). "In fact, in a later study a lack of association of heterozygous ATM mutations with early onset of breast cancer was found." (PMID 15642165, 2005). "Nevertheless, in the absence of information on the presence of any other ATM mutations associated with breast cancer in these patients, these results need to be interpreted cautiously." (PMID 14562025, 2003). "We conclude that ATM gene defects are not the major cause of radiotherapy complications in women with breast cancer." (PMID 9764584, 1998). "If the estimate that 4% of breast cancer cases are A-T gene carriers is correct, then ATM mutations do not confer clinical radiosensitivity." (PMID 9413938, 1997). "Breast cancer (BC) risk is significantly associated with pathogenic variants in at least eight susceptibility genes: BRCA1 (MIM#113705), BRCA2 (MIM#600185), PALB2 (MIM#610355), ATM (MIM#607585), CHEK2 (MIM# 604373), BARD1 (MIM#601593), RAD51C (MIM#602774), and RAD51D (MIM#602954)." (PMID 41230741, 2026). "Thus, MHT after natural menopause (as was studied in WHI) may be a clinically relevant option for ATM or CHEK2 PV carriers, and its potential impact on breast cancer risk should be further studied." (PMID 40298171, 2025). "However, they describe two cases who have PVs in moderate to low breast cancer risk genes (ATM/PALB2; case 119, ATM/FANCA; case 122) with bilateral breast cancer at age 35 and breast cancer at age 35 respectively – highlighting multiple and young onset cancers." (PMID 39843919, 2025). "Given the small number of PVs, we jointly analyzed two moderate penetrance genes, ATM and CHEK2, due to their shared association with ER-positive breast cancer in prior studies; the result of this exploratory analysis was an increase in breast cancer risk (OR = 7.3) associated with E + P MHT." (PMID 40298171, 2025). "However, no consensus was reached for recontact regarding breast cancer risk management in intermediate penetrance CSGs (ATM, CHEK2, RAD51C, RAD51D or BARD1)." (PMID 41159931, 2025). "Montani and colleagues found that ATM-depletion can sensitize breast cancer cells to PARP inhibition thus PARP inhibition could be of benefit in patients with low ATM protein expression/activity such as would be seen in heterozygous carriers of germline ATM mutation." (PMID 39085400, 2024). "Consequently, the dysregulation of ATM and RB1 might be a crucial factor underlying the resistance of HER2-positive breast cancer cells to trastuzumab." (PMID 39655080, 2024).
breast cancer (continued). "The primary objective of this study was to evaluate whether women with a monoallelic rare ATM PV or predicted PV and who underwent RT for non-metastatic breast cancer are at higher risk of acute and late toxicities than noncarriers." (PMID 38611095, 2024). "Interestingly, the breast cancer reference gene ATM is also one of the 1CM-involved genes." (PMID 39125744, 2024). "The tumor suppressor gene, BRCA1, a substrate of the ataxia-telangiectasia mutated (ATM) gene product, is part of a complex of molecules in the repair of DNA double-strand breaks (DSBs), and loss of BRCA1 contributes to progression of both, sporadic and inherited breast cancers." (PMID 39008483, 2024). "To date, however, there is a lack of understanding of whether early dysregulation of ATM/CHK2 predisposes formation of breast cancer that is treatment resistant or aggressively metastatic." (PMID 37390209, 2023). "While ATM and CHK2 are often paired together in canonical cell cycle regulation and DNA damage response, the results of our study suggest that they have distinct cellular functions that underlie their individual impact on breast cancer presentation and progression." (PMID 37390209, 2023). "Among the established breast cancer susceptibility genes, ATM yielded an odds ratio of approximately 8 for breast cancer overall and its estimated cumulative risks by 80 years of age exceeded the 30% threshold for high risk [(NICE) 2019], compared to published moderate-risk estimates for ATM PTVs." (PMID 37790698, 2023). "We conducted a genetic screen of ATM in the Australian Breast Cancer Family Registry (ABCFR), an Australian population-based case–control–family study of breast cancer, with the purpose of estimating the prevalence and penetrance of ATM pathogenic variants in this cohort." (PMID 35365198, 2022). "However, several of our premenopausal breast cancer patients carried germline variants of unknown/uncertain significance (VUSs) in eight different breast cancer susceptibility genes, namely BRCA1, BRCA2, CHEK2, RAD51C, RAD51D, ATM, BRIP1, and PMS2." (PMID 36011273, 2022). "However, loss of heterozygosity of the ATM gene as described, for example, for breast cancer has never been investigated in melanoma." (PMID 36555667, 2022). "Missense substitutions, selected from a breast cancer cohort and A-T patients, located in the C-terminal portion of ATM near or within its kinase domain, were reproduced in vitro by mutagenesis of full-length ATM cDNA and stably transfected into A-T and control cells." (PMID 34771661, 2021). "Regarding breast cancer, in addition to the known high-penetrance pathogenic variants of BRCA1/2, mutations in other high- or intermediate-penetrance genes can increase the risk of cancer and the most common non-BRCA pathogenic or likely pathogenic variants affect PALB2, ATM, and CHEK2 genes." (PMID 33800556, 2021). "This study identified putative pathogenic variants in ATM, BRCA1, BRCA2, CHEK2, and PALB2 as the most prominent genes for breast cancer, harboring protein-truncating variants that confer significant disease risks (odds ratio of 2.10 to 10.57) to overall breast cancer risk." (PMID 34439109, 2021). "To date, ATM alone has not been associated with a high incidence of contralateral BC, but genetic variants in ATM have been demonstrated to play a clinically significant role in radiation-induced contralateral breast cancer." (PMID 34068084, 2021).
breast cancer (continued). "Furthermore, mutations in moderate-penetrance genes such as BRCA1 interacting protein C-terminal helicase 1 (BRIP1), ataxia telangiectasia mutated (ATM), partner and localizer of BRCA2 (PALB2), and checkpoint kinase 2 (CHEK2) are associated with a two-fold increased risk of developing breast cancer." (PMID 33027908, 2020). "Similarly, a study in breast cancer patients showed that in patients with both hormone receptor-positive (HR+) and receptor-negative (HR-) breast cancer, low ATM expression by IHC was associated with HR negativity and poor OS." (PMID 33224881, 2020). "The pooled analysis showed no significant heterogeneity between studies (I2 = 25.8%; P = 0.206) and a non-significant effect of ATM rs1801516 on the risk of breast cancer patients to develop radiation-induced telangiectasia (pooled OR: 1.14; 95%CI: 0.88–1.48, P = 0.316)." (PMID 31756226, 2019). "However, the present updated meta-analysis with trial-sequential analysis shows for the first time that there is still insufficient information to draw reliable conclusions regarding the correlation between ATM rs1801516 and late skin toxicities induced by radiotherapy in breast cancer patients." (PMID 31756226, 2019). "However,other genes, such as ATM, PALB2, BRIP1, CHEK, BARD1, while lower in frequency, may also increase breast cancer risk." (PMID 29093764, 2017). "Further, radiation treatment induces the expression and activity of MET though ATM (ATM serine/threonine kinase)-NF-κB (nuclear factor kappa-light-chain-enhancer of activated B cells) signaling pathway, and consequently promotes invasion and apoptosis-resistance of breast cancer cells." (PMID 28872613, 2017). "Interestingly, the findings reported in this study suggest that ATM may represent a novel candidate target to impair the autophagic activity in Breast Cancer Stem-like cells independently of HER2." (PMID 28423511, 2017). "Moreover, in this experiment we showed that other ATM-dependent function could be involved in the regulation of Breast cancer stem-like phenotype." (PMID 28423511, 2017). "Although eQTL analysis has identified cis-eQTL associations between several variants and ACAT1, ATM as well as other neighboring genes in both breast carcinoma and normal breast tissues, none of these associations involved the most significantly associated risk SNPs." (PMID 27796716, 2017). "DNA samples from the primary breast cancer patients were also examined for the occurrence of loss of heterozygosity (LOH) for markers D11S897, D11S1818, and D11S2000 that span approximately 10 cM of the chromosomal region 11q22-23 where the ATM gene is located." (PMID 25625042, 2015).
breast cancer (continued). "Moreover, it has been proved that defects in ATM lead to poor differentiation of breast cancer." (PMID 25861265, 2015). "Furthermore, recent studies demonstrated that over-expression of microRNAs, such as miR181 and miR421, may be involved in ATM down-regulation in breast cancer." (PMID 25625042, 2015). "The breast cancer patient carrying a nonsense mutation was constitutively heterozygous for the mutation, but a DNA sample from her tumor showed LOH for the wild-type allele, which is consistent with the tumor suppressor role predicted for the ATM gene in the pathogenesis of breast cancer." (PMID 25625042, 2015). "However, many studies in the following years failed to convincingly associate ATM with breast cancer." (PMID 25247188, 2014). "Understanding the genome-wide miRNA profiles of normal and ATM-deficient non-cancerous mammary epithelial cells can help us gain a better understanding of the roles of ATM and miRNAs in the tumorigenesis of breast cancer and the transition from non-cancerous to malignant breast tissue." (PMID 23741392, 2013). "By comparison, individuals heterozygous for one of the many reported ATM null mutations have reduced levels of the ATM protein, albeit, these reduced levels do not always appear to fall below the threshold for risk of breast cancer and/or clinical radiosensitivity." (PMID 20678261, 2010). "We examined the mutation frequency of BRCA1, BRCA2, CHEK2 and ATM in women who had developed a second primary breast tumour at least 1 year after a first breast cancer diagnosed before the age of 50 years, with or without RT for their first breast cancer." (PMID 17428320, 2007). "The ataxia-telangiectasia mutated (ATM; MIM 607585), checkpoint kinase 2 (CHEK2; MIM 604373) and v-erb-b2 avian erythroblastic leukemia viral oncogene homolog 2 (ERBB2; also named HER2; MIM 164870) genes have been suggested to have an important role in breast cancer aetiology." (PMID 17132159, 2006). "One group found a relationship between poor breast cancer prognosis and common haplotypes in the ERBB2 gene, but to our knowledge, nothing has been reported regarding the association between common haplotypes in the ATM and CHEK2 genes and breast cancer survival or tumour characteristics." (PMID 17132159, 2006). "The study of 270 Austrian breast and ovarian cancer families reported a significant prevalence of ATM mutations in these families, whereas no ATM mutations associated with increased breast cancer risk were found in 121 breast or breast-ovarian cancer families from Northern Finland." (PMID 16914028, 2006). "Although the gene products of ATM, CHEK2 and ERBB2 are involved in various aspects of breast cancer development and progression, our results suggest that common variation in these genes does not affect survival, tumour-characteristic-defined risk or the overall risk of breast cancer." (PMID 17132159, 2006). "Mutations in the ataxia-telangiectasia mutated (ATM) and checkpoint kinase 2 (CHEK2) genes and amplification of the v-erb-b2 avian erythroblastic leukemia viral oncogene homolog 2 (ERBB2) gene have been suggested to have an important role in breast cancer aetiology." (PMID 17132159, 2006).
breast cancer (continued). "Although ATM heterozygosity in relatives on average was estimated to infer a significant 2.9-fold increased risks for breast cancer, if causal, our data did not convincingly point to a trend of increasing risk with each increment in the probability of being an ATM mutation carrier." (PMID 15942625, 2005). "The existing international data on the risks for breast cancer of other female relatives are, however, still not conclusive, and convincing data to support a simple relationship between likelihood of ATM heterozygosity and risk of breast cancer has not yet been presented." (PMID 15942625, 2005). "More recent epidemiological studies suggested that missense mutation in the ATM gene, rather than a protein-truncating mutation, which accounts for the majority of mutations in patients with ataxia-telangiectasia, confers increased risk for breast cancer." (PMID 15642165, 2005). "Confounding could also arise if the mothers of children with AT were more likely to undergo screening examinations for the early detection of breast cancer than the general population, because clinicians might be aware of the suggested link between ATM heterozygosity and breast cancer." (PMID 15942625, 2005). "Thus, cancer risk in ATM heterozygotes varies depending on the mutation type (i.e. some missense-type mutations are associated with early onset of breast carcinoma whereas truncation-type mutations are not)." (PMID 15642165, 2005). "However, the probability of finding ATM and BRCA1 mutations in sporadic breast cancer is low." (PMID 15138484, 2004). "While not all studies of ATM gene mutations demonstrate an excess risk of breast cancer, studies that have screened for missense mutations and those that have examined risk among family members of A-T patients (obligate heterozygotes) have consistently found an elevated risk." (PMID 14562025, 2003). "Heterozygous carriers of the ataxia-talangiectasia gene ATM have been reported to be at increased risks of breast cancer and there is also evidence that rare HRAS1 alleles may be associated with moderate risks for breast cancer." (PMID 11857015, 2002). "In breast cancer models, BAK acts as a selective phytoestrogen, induces S-phase arrest, activates the ATM/ATR-Chk1/Chk2 axis, and triggers mitochondrial apoptosis, particularly in ERα-positive cells." (PMID 41594634, 2026). "XRCC1 loss amplifies the sensitivity of pancreatic cancer cells to β-lapachone, triple negative breast cancers to the ATM, ATR, and Wee1 inhibitors, liver adenocarcinoma HepG2 to γ rays, and breast cancer cells to cisplatin, camptothecin, and MMS." (PMID 40271221, 2025). "Moreover, miR-943 is negatively correlated with the gene expression of Ataxia-telangiectasia mutated (ATM) and breast cancer gene 1 (BRCA1) in BC, which suggests its potential involvement in the repair of DNA double-strand breaks." (PMID 40143252, 2025). "For breast cancer, there were 6 genes with a posterior probability > 0.9: BRCA2, BRCA1, PALB2, CHEK2, ATM, and MAP3K1." (PMID 40073867, 2025). "Two patients, one with a CHEK2-PV and one with an ATM-PV, had bilateral breast cancer, rendering the MFRA for breast cancer obsolete." (PMID 40805171, 2025). "Of the 307 patients with breast cancer, 33% had VUS, primarily in ATM (12%), BRCA2 (11%) and BRCA1 (5%)." (PMID 40259910, 2025). "This idea is supported by experimental evidence in breast cancer cells, where the lncRNA RAMP2-AS1, was shown to bind and inhibit miR-660-5p, allowing increased ATM production." (PMID 41065894, 2025). "Previous studies have shown that GNAI2 regulates EMT in pancreatic and breast cancer via ERK signaling, and GNAI1 impacts DNA damage repair via ATM/CHK2 pathway modulation in glioblastoma." (PMID 40819057, 2025). "Currently, a variety of cell cycle checkpoint kinase inhibitors are also under research and their anti-tumor effects in combination with PARP inhibitors are evaluated, including inhibition of CHEK1/2, ATM, ATR, and WEE1 in breast cancer." (PMID 39334297, 2024).